IL2 (interleukin 2)
Diseases named in the same sentence as IL2 in open-access papers (continued):
Sharing a sentence is not in itself a finding about the gene and the disease.
sarcoidosis (continued). "Levels of IL-1β and IL-10 were significantly elevated in both diseases compared to healthy BALs, whereas levels of IL-2 were significantly increased in sarcoidosis only." (PMID 22815689, 2012). "In this study, we demonstrate a decreased mRNA and protein level of TIM-3 in BALF CD4+ T cells of sarcoidosis patients with active disease, while IL-2 mRNA expression was elevated." (PMID 19480659, 2009). "There was a significant increase in the relative expression of IL-2 mRNA in CD4+ T cells from sarcoidosis patients compared with controls (p = 0.008)." (PMID 19480659, 2009). "Granuloma formation in sarcoidosis is mediated by increased secretion of interferon-gamma, interleukin-2, and tumor necrosis factor-alpha." (PMID 18226232, 2008). "The immune response in the pathogenesis of sarcoidosis is characterized by a bias toward the Th1 response, with the release of cytokines and chemokines associated with this type of immune response (e.g., IFN-γ, TNF-a, and often IL-2)." (PMID 37761266, 2023). "Pulmonary CD4+ T cells from sarcoidosis spontaneously secrete IL-2 ex vivo, but when given TCR stimulation, these cells express less IL-2 and IFN-γ relative to CD4+ T cells from various other lung diseases and healthy control subjects, consistent with an anergic/exhausted phenotype." (PMID 32256501, 2020). "In particular, interleukin-2 (IL-2) secretion by activated T-cells is thought to play a role in the pathogenesis of sarcoidosis and may be a mechanism linking sarcoid-like granulomatous reactions to immunotherapy." (PMID 26981243, 2016). "In active sarcoidosis, the expansion of the natural Treg cell subset may account for anergy by abolishing IL-2 production and strongly inhibiting T cell proliferation." (PMID 22927996, 2012). "Based upon the literature, we developed a computational model of known interactions between essential immune cells (antigen-presenting macrophages, effector and regulatory T cells) and cytokine mediators (IL-2, TNFα, IFNγ) of granulomatous inflammation during sarcoidosis." (PMID 21637752, 2011). "considers the progression of sarcoidosis in terms of a granuloma radius represented as a conglomerate of Mφ, Th1, Treg and Th17 cells, which affect each other through a network of cytokines and chemokines (IL-2, IL-10, IL-12, IL-13, chemokine ligand 20, IFN-γ, TNF-α and TGF-β)." (PMID 38550585, 2024). "Indeed, the disease activity of a preexisting sarcoidosis may also be increased by high dose IL-2 treatment of neoplasia and human immunodeficiency virus (HIV) infection." (PMID 26981243, 2016). "Therefore, studies have shown increased serum concentrations of IL-1 IL-2 in sarcoidosis patients." (PMID 23691415, 2013). "The inflammatory response in sarcoidosis is characterized by the increased production of several inflammatory cytokines produced by type 1 helper T (Th1) cells and macrophages, such as interleukin-2 (IL-2), interferon-gamma (IFN-γ), and tumor necrosis factor alpha (TNF-α)." (PMID 22393278, 2012). "Thus, assuming that the modeling conditions accurately depict the mechanisms regulating granuloma formation in the setting of sarcoidosis, careful titration of combination therapy with anti-IL-2 and anti-IFNγ is predicted to effectively attenuate disease activity." (PMID 21637752, 2011). "The pathophysiology of sarcoidosis involves activation of macrophages and CD4+ T lymphocytes, leading to increased production of tumor necrosis factor-alpha (TNF-α), interleukin-2 (IL-2), interferon-gamma (IFN-γ), and serum amyloid A protein." (PMID 40988789, 2025). "As high levels of IFN-γ, IL-2, tumor necrosis factor (TNF)-α, and high T-cell expression of chemokine receptors CXCR3 and CCR5 were found in BALF, sarcoidosis was initially considered a Th1-driven disease." (PMID 40217830, 2025). "Sarcoidosis patients had decreased levels of IL-1β, IL-5, IL-8, IL-12p70, TNF-α, angiogenin, C3a, C4a, RANTES, and MCP-1 and increased levels of IL-2, IL-4, IL-6, IL-13, IFN-γ, and VEGF." (PMID 40725075, 2025).
sarcoidosis (continued). "Early phases of sarcoidosis are characterized by a Th1-promoting milieu of chemokines such as IL-2 and IFN-gamma, which led to sarcoidosis being classically viewed as a Th1-polarized disease." (PMID 37089604, 2023). "Granulomas were histologically similar to those observed in sarcoidosis with the recruitment of macrophages, CD4+ T lymphocytes with Th1 cytokine (IL-2 and IFNγ) production, and rare B lymphocytes." (PMID 32751786, 2020). "To more carefully assess the capacity of sarcoidosis CD4+ T cells to produce cytokines, we compared spontaneous versus TCR-stimulated IL-2 and IFN-γ production." (PMID 29234685, 2017). "Despite spontaneous secretion of Th1 (and Th2) cytokines such as IL-2 and IFN-γ, sarcoidosis CD4+ T cells demonstrate suboptimal Th1 cytokine production and proliferation following T cell receptor (TCR) stimulation during active disease." (PMID 29234685, 2017). "Intracellular staining for IL-2 and IFN-γ production in matching sarcoidosis BAL and PBMC was conducted at baseline and after TCR stimulation." (PMID 29234685, 2017). "In regressing sarcoidosis, relationships were observed between T-bet and IL2RB, IL15RA, CXCR3, IL2, and IFNG." (PMID 26696750, 2015). "A second mechanism in sarcoidosis is that granulomas are characterized by local proinflammatory activated CD4 + T lymphocytes with Th1 profile (IFNγ, IL2) stimulating TNFα production by macrophages." (PMID 24373564, 2013). "Interleukin-2 production and interleukin-2 receptor expression of BAL cells stimulated by the P. acnes antigen was greater in sarcoidosis patients than in healthy subjects or patients with other lung diseases." (PMID 23844371, 2013). "Elevated levels of IL-2, TNF-α, and other pro-inflammatory molecules are frequently observed in sarcoidosis and may serve as indicators of disease activity or progression." (PMID 40078389, 2025). "Moreover, patients who spontaneously recovered from sarcoidosis exhibited normalized levels of Lck, PKC-θ, and NF-κB as well as proper response to TCR stimulation by secretion of IL-2 and IFN-γ that approached healthy control levels." (PMID 33036432, 2020). "Sarcoidosis is a multi-system disease characterized by noncaseating granulomatous inflammation in a Th1/Th17 cytokine environment with elevated levels of IL-2, IL-12, IL-17, TNF- α, and IFN-γ." (PMID 31963936, 2020). "Pulmonary CD4+ T cells from patients with sarcoidosis spontaneously secrete IL-2 ex vivo, but upon TCR stimulation, they express less IL-2 and IFN-γ compared to CD4+ T cells from other lung diseases and healthy controls, in line with an anergic/exhausted phenotype." (PMID 32722050, 2020). "Laboratory markers, like lysozyme and soluble interleukin 2, were not routine examinations for the patients with sarcoidosis in our clinical setting." (PMID 29785303, 2018). "Because non-Löfgren’s syndrome sarcoidosis patients only exhibited a higher CD8+ T-cell-mediated lysis rate upon pre-stimulation by IL-2, it can be assumed that these sarcoid CD8+ T-cells lacked IL-2 beforehand—supporting the concept that inadequate TH1 cell stimulation is the culprit." (PMID 33036432, 2020). "An anergic/abnormal TH1 cell response—also correlated with poor sarcoidosis outcomes—could explain inadequate CD8+ T-cell stimulation as well, since a normal TH1 cell response is necessary to stimulate CD8+ T-cells through production of IL-2." (PMID 33036432, 2020).
Allergy (53 papers, 2005 to 2025). An allergy is an immune response or reaction to substances that are usually not harmful. "CD16 upregulation of eosinophils has been linked to pro-inflammatory cytokines (IFN-γ, IL-2), IgG immune complexes, states of allergy and soil-transmitted helminth infection." (PMID 38771861, 2024). "In addition, since TLR6 and IL2 were earlier associated with other later onset allergies, this also favours the “allergic march” hypothesis." (PMID 26941931, 2015). "The results suggest that the body weight and thymus index returned to normal levels; allergy scores, serum OVA-sIgE, IL-4, IL-5, and IL-10 expression decreased; and IFN-γ and IL-2 increased significantly in the ZW3 group compared with the allergy group." (PMID 39796306, 2024). "The authors of that study evaluated the effectiveness of spirulina by assessing the production of crucial cytokines (interleukin [IL]-4, IFN-γ, and IL-2) involved in regulating IgE-mediated allergy." (PMID 38611357, 2024). "In fact, several strategies used IL-2 to expand regulatory T cells to treat autoinflammatory and allergic diseases." (PMID 37090735, 2023). "IL-2 promotes the function and survival of regulatory T cells (Tregs), which play a role in preventing allergic diseases, such as AR and AD, by regulating immune homeostasis." (PMID 36107283, 2023). "The results of a study show that intranasal use of SP-D reduced inflammatory symptoms and allergies in mice and also reduced IL-2, IL-4, IL-5, and eosinophil levels." (PMID 35419072, 2022). "B cells in that cluster had a decreased expression of IL-2 in the allergy groups, reaching statistical significance only in the IgEneg group." (PMID 32698761, 2020). "Humanized TCR/HLA‐transgenic allergy mice were treated in vivo with recombinant IL‐2 complexed to the anti‐IL‐2 mAb JES6‐1 in the presence or absence of mugwort pollen extract (MPE) on days 0‐2." (PMID 31991489, 2020). "After manual gating of CD4+ T, CD8+ T and NK cells according to S. Figure IIA, there was a reduction of TNF-α + IFN-γ+, IL-2+ cells in both allergy groups, reaching statistical significance only in the IgEneg allergy group." (PMID 32698761, 2020). "This study demonstrated that ld-IL-2 is efficient to prevent and to treat allergic immune responses, and thus represents a promising therapeutic strategy for managing allergic diseases for human in future." (PMID 29527328, 2018). "Due to this central role in regulating the immune response, IL2 is considered a strong candidate gene for allergic disease." (PMID 25238536, 2014). "The grade III AEs consisted of allergy to IL-2 (one, group D), and neutropenia (three—one in group A and two group C)." (PMID 17260026, 2007). "This study compared Th1 (IL-2) and Th2 (IL-4) parameters, anti-inflammatory, pro-inflammatory, or regulatory profile regarding both IgE levels and reported allergies, by means of clinical manifestations and IgE, IL-1β, IL-2, IL-4, IL-17, and TGF-β serum concentration." (PMID 34518597, 2021). "Therefore, we here evaluated in a humanized preclinical model of allergy the co‐administration of IL‐2/αIL‐2 complexes and allergen and how this would impact on the course of the allergic disease." (PMID 31991489, 2020). "Our observation that IL-2-induced IFN-γ can exacerbate food allergy may appear to contradict previous observations that endogenously produced IFN-γ inhibits allergy." (PMID 33362780, 2020). "This is the first humanized allergy model in which, upon natural induction, IL-2-αIL-2 complexes could alleviate both sensitization and disease." (PMID 29678672, 2018). "If a patient is having a mild allergic reaction, the rate of dinutuximab should be decreased by half and the cytokine (GM-CSF or IL-2) may continue at its full rate." (PMID 29900016, 2017).
Allergy (continued). "The roles of TSLP and IL33 in allergy were evaluated in TSLP receptor (TSLPR)- and IL33 receptor-deficient (T1/ST2) mice, respectively; TSLPR- and T1/ST2-knockout mice showed strong Th1 responses with high levels of IL2 and IFN-γ and impaired the Th2 response." (PMID 27826297, 2016). "The present results showed an important association between SNPs in cytokine genes and susceptibility to or protection from allergy to dust mites in IL1A at position −889, IL4RA at position +1902, IL2 at positions −330 and +166, IL4 at position −590, and IL10 at position −592." (PMID 25238536, 2014). "Indeed, Tregs expansion by IL-2/anti-IL-2 is protective in experimental models of allergy and for the kidney it has been utilized with positive results in experimental crescentic glomerulonephritis and in the renal ischemia-reperfusion injury." (PMID 25343479, 2014). "In experimental studies on different models of allergic diseases, gallic acid is demonstrated to suppress of allergen induced hypersensitivity reactions in mice and inhibit release of histamine and helper T cell subtypes, IL-4, IL-5 and IL-2 form human mast cells." (PMID 27536321, 2016). "In turn, the histamine increases the secretion of Th2 cytokines such as IL-4, IL-5, and IL-13 and inhibits the production of the Th1 cytokines IL-2 and IFN-γ through the upregulation of prostaglandin E2 and nitric oxide, thereby exacerbating the allergy." (PMID 39403377, 2024). "Dialister was negatively related with RQLQ at week 14 and positively related with anti-inflammatory factor IL-2 at week 14 as well as IFN-γ at week 34, which appear to protect against allergies." (PMID 34745150, 2021). "These cells produce cytokines characteristic of the Th1-dependent response (IL-2, IFN-γ) and Th2 cells (IL-4, IL-5, IL-10) so they can play both protective and pathogenetic roles in allergic diseases, depending on the disease phase." (PMID 33435598, 2021). "An important issue that needs to be emphasized considering in vitro tests is the fact that cytokines are determined in various conditions and various diseases; however, only certain cytokines (i.e., TNF-α, IL-2, IL-4, IL-5, IL-6, IL-10, IL-13, and IFN-γ) are important in allergic reactions." (PMID 36590449, 2022). "An increase in regulatory cytokine IL-2 and TGF-β was detected, as was the reduction of IL-4, IL-17, and IL-1β, reflecting the cancer patient's immunosuppressive environment and the lower prevalence of allergies." (PMID 34518597, 2021). "This hyporesponsiveness of ILC2s did not occur when the basal ILC2 activity was maintained by IL-2 and IL-7 without IL-33, which is a strong inducer of allergy." (PMID 30683858, 2019). "Current studies indicates that genetic variation of TLR6 and IL2, which were earlier reported to be associated with non-CMA allergies and/or allergy sensitization, contribute to the expression of CMA in young children." (PMID 26941931, 2015). "Therefore, downregulation of iNOS, IL-2, TNF-α, and IFN-γ expression has been used to predict the favorable effects of test materials in patients with various allergic diseases." (PMID 26221169, 2015). "Histamine is responsible for inflammation in allergic reactions in general, but bacteria-metabolized histamine has been shown to inhibit the production of pro-inflammatory cytokines such as TNF-α in vivo and IL-1 and IL-2 in vitro, in addition to preventing intestinal bacterial translocation." (PMID 37161621, 2023). "The balance of Tfh and Th1 cell differentiation in vivo is regulated by IL-2 signaling through PI3K, AKT and mTOR, and both mTORC1 and mTORC2 essentially promote Tfh cell differentiation and germinal centers (GC) formation, which cannot be ignored in allergic diseases." (PMID 36964157, 2023). "In addition, certain cytokines which induce the pathological immune stimulation status such as allergy and autoimmune disorders such as IL-2, -4, -5, and IL-7 were not changed." (PMID 26173062, 2015).
Allergy (continued). "In mice attenuation of OVA-induced allergy (IgE-specific Ig and OVA-induced IL-4) was seen using both mouse and human Ig mixtures, without effect on OVA serum IgG or OVA-induced IL-2." (PMID 32377529, 2020). "At variance with IL-2, IL-33 did not stimulate MC for IL-9/TGF-β production, a finding indicating a minor contribution of the IL-33/MC axis in promoting inflammatory allergy and pathology in response to the fungus." (PMID 28090087, 2017). "Accordingly, FACS-sorted, naïve CD62L+CD25-CD44-CD4+ T cells from transgenic allergy mice were co-incubated with syngeneic BMDC in the presence of cognate Art v 1 protein in the presence or absence of BX-795 with and without IL-2 and/or TGF-β1 neutralizing antibodies for 5 days." (PMID 37090735, 2023). "Thus, in the context of colonic inflammation and limited IL-2 signaling, CD8+ T cells differentiate into non-classic TC2 that may contribute to the pathology of inflammatory/allergic diseases in children." (PMID 29922282, 2018).